IL6 (interleukin 6)
Diseases named in the same sentence as IL6 in open-access papers (continued):
Sharing a sentence is not in itself a finding about the gene and the disease.
cancer (continued). "In the negative group, most cancer cells were negative for a IL-6 immunoreactivity whereas stromal cells around the cancer nests expressed IL-6 slightly." (PMID 25761055, 2015). "Flagellin governs the proliferation of T cells and cancer cells by upregulating cytokines and chemokines, including TNF-α and IL-6, and the role of mTOR signaling in flagellin-induced inflammatory responses is unknown." (PMID 25942007, 2015). "Furthermore, the expression of p-STAT3 was investigated in the nucleus of the cancer cells, suggesting that STAT3 signaling is activated through autocrine loop stimulation between IL-6 and IL-6R in OSCC cells." (PMID 25761055, 2015). "Serum IL-6 levels were higher in fat losing gastrointestinal cachectic cancer patients compared to weight stable and noncancer controls." (PMID 26508820, 2015). "Administration of IL-6 to nonhuman primates and cancer patients resulted in a decrease of total cholesterol levels." (PMID 26322890, 2015). "They found that the plasma concentration of IL-6 was 11.4 times higher in the cachectic cancer group compared with the groups without cancer and with healthy weight, in addition to demonstrating a significant correlation with the presence of cancer." (PMID 26508818, 2015). "Moreover, several inflammatory cytokines such as TNF-α, IL-6, TGF-β, and IL-10 have been shown to participate in both the initiation and progression of cancer." (PMID 26528286, 2015). "In addition, interleukin-6 (IL-6) and its family members were recently identified as regulators of JAK-STAT signaling in cancer." (PMID 26580615, 2015). "To test whether IL-6, one of the main SASP factors, contributes to the cancer promoting effect of the SASP and the ERK1/2 pathway activation, we added recombinant IL-6 to CMns-treated MCF7 cells and an anti-IL-6 antibody to CMsn-treated MCF7 cells." (PMID 26658759, 2015). "We chose ERK, TGFB1, TGFB2, SIRT1, IL-6, PI3K, and WHSC1 (which were controlled by several genes) and three other genes AR, BCL-XL, and CCND1 that could mark the deterioration of the cancer, for testing." (PMID 26603105, 2015). "In line with this, previous studies demonstrated that IL-6 expression might be inhibited by Jagged-1 and HGF in macrophages, or by IDO in DC, though IDO presents the opposite effect in human cancer cells." (PMID 26060498, 2015). "Moreover, preclinical cancer mouse models indicate that blockade of IL-6- and IL-11-STAT3 signalling cascades is a promising strategy in development of cancer therapies." (PMID 28781374, 2015). "Blockage of the IL-6/STAT3 signaling pathway might be a promising approach to decrease or prevent the recurrence and metastasis of cancer after chemotherapy." (PMID 26016502, 2015). "Exogenous treatment of IL-6 (100 ng/ml, 72h) significantly stimulated VEGF production from cancer cells (control; 239.4 ± 16.3 pg/1x 105 cells, IL-6; 322.4 ± 11.8 pg/1x105 cells) and the pretreatment of cancer cells with anti-IL-6R antibody significantly inhibited VEGF production." (PMID 25658637, 2015). "Serum IL-6 level was independent of the patients’ age, gender, smoking and drinking history as well as cancer stage." (PMID 26082902, 2015). "By ELISA or flow cytometric bead-based immunoassays, we quantified the media concentrations of three permeability-inducing and/or pro-inflammatory cytokines, whose elevated levels in cancer patients often correlate with disease progression and poor prognosis: VEGF, IL-8, and IL-6." (PMID 25851538, 2015). "Interestingly, IL-6, IL-6R and p-STAT3 were expressed in the residual cancer cells of all the patients in the high expression group with poor response to chemoradiotherapy." (PMID 25761055, 2015). "Untreated osteoblasts in vitro and osteoblasts lining the bone marrow in vivo release a variety of cancer promoting cytokines such as interleukin-6 (IL-6) and monocyte chemotactic protein-1 (MCP-1), both of which have also been shown to promote cancer cell migration and invasion." (PMID 24740307, 2014).
cancer (continued). "The constitutive nuclear activation of NF-κB could also play a major role in the endogenous expression of chemokines, interleukins IL-1, IL-6 and VEGF hence, lead to the pathogenesis of cancer." (PMID 24416253, 2014). "In mammals, the cytokine interleukin-6 and its downstream effector STAT3, a homologous pathway of the Drosophila Upds/JAK/STAT signalling, are involved in inducing intestinal inflammation and cancer." (PMID 24586740, 2014). "While cytokines such as TNF-α and IL-6 have been known to mediate cancer cachexia, SJDBT reduced IL-6 level without altering TNF-α." (PMID 24963216, 2014). "We identified Toll-like receptor 1 (TLR1), TLR2, TLR4 and TLR8 gene expression levels and downstream gene, i.e., interleukin-6 (IL-6), IL-8, interferon-α (IFN-α) and myeloid differentiation primary-response protein-88 (MyD88), expression levels in CRC patients and in cancer cell lines." (PMID 25547486, 2014). "In summary, low levels of SOCS3 do not appear to be involved in the induction of IDO by IL-6 in the human cancer cells and tissues analyzed." (PMID 24657910, 2014). "The accumulation of the proinflammatory cytokine IL-6 in the extracellular medium of the C-26 cancer cells was not unexpected." (PMID 24967341, 2014). "Furthermore, treatment of cancer cells with EGFR inhibitors such as afatinib and dacomitinib can activate the IL-6/JAK/STAT3 signaling pathway, which in turn induces resistance to these agents." (PMID 24662938, 2014). "However, most studies into the mechanisms of inflammation-driven metastasis have focused on the induction of chemokine receptors, which can direct the movement of cancer cells, by inflammatory cytokines such as TNF-α, IL-1β and IL-6." (PMID 24789104, 2014). "When combined together, AG14361 and lestaurtinib exhibited a much stronger inhibitory effect on the expression of a number of genes in the NF-κB signaling pathway, such as p50, p65, IL6, IL8, COX2 and MMP9 that are involved in cancer cell proliferation, inflammation, invasion and/or cell death." (PMID 24962108, 2014). "In addition, top three canonical pathways related to the gene sets are molecular mechanisms of cancer, LPS-stimulated MAPK signaling, IL-6 signaling, iNOS signaling, EIF2 signaling and mTOR signaling." (PMID 24416147, 2014). "IL6 and IFN are crucial for skin inflammation and other inflammation related cancer." (PMID 24962779, 2014). "IL-6 activates the release of hepatic GSH and its interorgan transport to the growing cancer cells." (PMID 24802641, 2014). "In addition, IL-6-induced dimerization of IL-6 receptor activates STAT3, which contributes to cancer progression in cancer inflammatory environment." (PMID 24976685, 2014). "Importantly, JAG1 expression can be induced by other signaling pathways that are important in cancer such as TGF-β, WNT/β-catenin, IL-6, and NF-κB, as well as by the Notch pathway itself." (PMID 25309874, 2014). "Moreover, an autocrine signaling loop involving IL-6, STAT3, and AhR was found to sustain the constitutive expression of IDO1 in human cancer cells." (PMID 25360135, 2014). "Immunohistochemical staining revealed that carcinoma cells themselves produce IL-6 regardless of the types of carcinoma cells." (PMID 25328756, 2014). "IL-1β is also known to promote cancer progression by upregulating pro-metastatic genes such as matrix metalloproteinases and stimulate adjacent cells to produce angiogenic proteins or growth factors including VEGF, IL-8, IL-6, TNF-α and TGF-β." (PMID 23495140, 2013). "The anti-cancer kinase inhibitor sorafenib inhibits replication of HCMV at clinically relevant concentrations and, in contrast to ganciclovir, suppresses HCMV immediate-early antigen (IEA) expression, which is involved in IL-6 production." (PMID 23555719, 2013). "Neither YKL-40 nor IL-6 is a cancer-specific biomarker, and both are produced by cancer cells and inflammatory cells and are biomarkers of inflammation and tissue remodeling." (PMID 23840582, 2013).
cancer (continued). "An increase in IL-6 was also observed in patients without cancer undergoing anesthesia with sevoflurane." (PMID 23374147, 2013). "Epidemiological data also supported the role of IL-6 and TNF-α in cancer promotion." (PMID 24205276, 2013). "Accordingly, a combination of IL-6 pathway blocker and EGFR-TKI may show more favorable effects in cancer patients." (PMID 23592411, 2013). "High plasma concentrations of YKL-40 and IL-6 are independent prognostic biomarkers associated with short OS in patients with many different types of cancer, but only a few studies have evaluated the prognostic value of plasma YKL-40 and IL-6 in patients with PCs." (PMID 23840582, 2013). "A previous study observed the production of cytokines in cancer cell lines (PANC-89 expresses IL-6 but not TGF-β, whereas PANC-1 expresses TGF-β but not IL-6)." (PMID 24179494, 2013). "Moreover, elevated levels of IL1, IL6 and IL8 were shown to be correlated with aggressive cancer behavior and poor prognosis." (PMID 23799116, 2013). "The level of IL-6 in tissue specimens (six paired cancer and adjacent nonmalignant tissue specimens) was examined using mRNA and protein analyses." (PMID 23637926, 2013). "Il-6, Il-6ra and Prdm1 were specifically up-regulated in disseminated tumors cells but not in carcinomas, suggesting de novo expression of these genes in the microenvironment of the distant organ." (PMID 23520493, 2013). "Here, we show for the first time, that the CSC-like sphere cells of PC cells produce a significant amount of IL-6, compared to its parental non-sphere cancer cells under hypoxic conditions." (PMID 23272057, 2012). "Interleukin 6 (IL6) plays an important role in immunoregulation and tumorigenesis in human cancers." (PMID 23185547, 2012). "Similarly, production of pro-inflammatory cytokines (IL-6, IL-8, IL-12p70, TNF-α and IL-1β) was strongly inhibited by TLR7 ligand in two cancer-derived HPV cell lines." (PMID 22513098, 2012). "It has also been reported that BQ chewing contributed to the pathogenesis of cancer and OSF by impairing T cell activation and by induction of prostaglandin E2 (PGE2), TNF-α and IL-6 production, which affect oral mucosal inflammation and growth of oral fibroblasts/oral epithelial cells." (PMID 22912735, 2012). "Although IL6 is a well characterized inflammatory target gene for TNF-α, and bleomycin-induced fibrosis is ameliorated in Tnfr−/− mice, B cell infiltrates also fuel IL-6-mediated and Stat3-dependent cancer growth following the release of lymphotoxin (LT)." (PMID 22684844, 2012). "The body redox systems, which include antioxidant enzymes and low molecular weight antioxidants, may be deregulated in cancer cells along with TNF-α and IL-6." (PMID 21350723, 2011). "Treatment with GL tended to increase mitogenic reactivity to phytohemagglutinin, counts of CD3, CD4, CD8 and CD56 lymphocytes, plasma concentrations of interleukin (IL)-2, IL-6 and interferon (IFN)-γ, and NK activity, whereas plasma concentrations of IL-1 and TNF-α were decreased in cancer patients." (PMID 19617199, 2011). "Gene expression profiles in such cells are likely to be representative of the genetic profile of a cancer cell with aberrant STAT3 expression, as compared to inducing STAT3 activity transiently using exogenous stimulation, such as IL-6 or transient transfection." (PMID 22046235, 2011). "IL-6 is known to be a mediator of PCA morbidity, and may act as a cell growth factor and protect cancer cells from death." (PMID 21943235, 2011). "Regardless, IL-6 is likely not the only cytokine mediating muscle wasting in cancer or even in the C26 model." (PMID 21799891, 2011).
cancer (continued). "Analysis of ROC curves indicates that IL-7 (p = 0.0039), but not IL-6 (p = 0.2938) or IL-15 (p = 0.1804) titres were able to distinguish sera from patients with malignancy from those from patients with benign disease." (PMID 21943235, 2011). "Additionally, the IL-6 signaling pathway involving STAT3 had a significant number of contributing methylated genes, a pathway recently found to play a significant role in cancer stem cell regulation." (PMID 20929579, 2010). "In the report by Warne, mRNA expressions of IL-6 and other cytokine and leukocyte markers were not altered in cachectic patients with cancer, and no major fat cell death was present either." (PMID 21197447, 2010). "Gene ontology, molecular network and canonical pathway analysis of NASP overexpression demonstrated that the most significant changes were in proteins participating in organismal injury, immune response, and cellular growth and cancer pathways (major "hubs": TNF, FOS, EGR1, NFκB, IRF7, STAT1, IL6)." (PMID 19439102, 2009). "Numerous studies emphasize the important role of IL-6 and TGF-β1 in the pathophysiology of cancer." (PMID 18682839, 2008). "In carcinoma cell lines, the major trends included a strong STAT3 activation by LIF (ADLC, H125), an increased (ADLC, H23) or decreased STAT3 activation by IL-6 (H125, H324), a decreased ERK activation by EGF (H522), and a treatment-independent, constitutive activation of the ERK pathway (H23)." (PMID 16271139, 2005). "In that JAKs play an essential role in driving oncogenic Stat3 signalling, the ability of 15d-PGJ2 to downmodulate IL-6/JAK signalling may also in part, explain the antineoplastic properties of this agent against other types of human cancer." (PMID 15316561, 2004). "Since interleukin-6/STAT3 signaling is known to stimulate prominin-1 expression, prominosome-mediated cancer cell–macrophage communication could create a positive feedback loop that further enhances cancer growth and metastasis." (PMID 39881297, 2025). "Indeed, the local microenvironment may promote cancer progression by aberrant communication within the tissue, and IL‐6, IL‐8, and CXCL1 were identified as the link between cancer and wound healing." (PMID 40621923, 2025). "An increase in IL-6 from PA, not OA, indicates that PA could drive cancer progression to a greater extent than OA." (PMID 40381373, 2025). "Furthermore, the levels of multiple cytokines, including IL-2, IL-4, IL-6, IL-10, TNF, and IFN-γ in the supernatant of the OHSV2-DSTEFAP5/CD3 group co-cultured with cancer cells and fibroblasts, showed a significant increase compared to groups with either cell type alone." (PMID 40406146, 2025). "Ingenuity pathway analysis (IPA) detected downregulation of many canonical pathways related to growth and cancer, including Wnt/β‐catenin, EGF signalling, TGF‐β signalling as well as repression of inflammatory pathways such as TNFR1 signalling, TNFR2 signalling and IL‐6 signalling." (PMID 39508147, 2025). "Interestingly, for six genes (KISS1, CXCR4, PSMB9, ABCB1, FGF2, and IL6) found to be up-regulated along with GCS, their overexpression pursuant to platinum-agent treatments in patients promoted resistance to those same agents in cancers." (PMID 40507922, 2025). "In addition, the pathological effects of IL-6 on C2C12 differentiation would be reversed in the presence of DTT water extract, which could explain the protective effects of DTT water extract in cancer-induced muscle wasting." (PMID 41226740, 2025). "However, the patient’s suboptimal response to glucocorticoids and IL-6 inhibitors, along with a negative cancer workup, made AOSD and hematologic malignancies less likely." (PMID 40927711, 2025).
cancer (continued). "Similarly, interleukin 6 (IL-6) released by M2-type TAMs enhances the cyclooxygenase-2 (COX-2) and prostaglandin E2 (PGE2) expression in cancer cells, which has been demonstrated in promoting the nuclear translocation of β-catenin and stimulating EMT in NSCLC cell lines." (PMID 41023740, 2025). "Such experiments, combined with knockout mice lacking specific immune receptors (e.g., TLR4, IL-6), could clarify which inflammatory pathways are indispensable for microbiota-driven cancer promotion." (PMID 41374093, 2025). "Regular PA stimulates the release of skeletal muscle-derived IL-6, which inhibits the release of pro-inflammatory factors (TNF-α and IL-1β) and promotes the release of the anti-inflammatory factor IL-10, inducing an anti-inflammatory environment and improving health outcomes in cancer survivors." (PMID 39896788, 2025). "Finally, we found a statistically significant inverse correlation between CTCF and IL6 expression levels in BrCa tissues from patients with good prognoses, but not in those with cancer recurrence." (PMID 40143084, 2025). "Notably, 2-HBA positively correlated with all inflammatory markers, including IL-6, contradicting previous reports where this non-flavonoid polyphenol was shown to play a role in modulating both inflammation and cancer proliferation." (PMID 41403880, 2025). "This evidence positions IL-6 not merely as a biomarker, but as a central mechanistic node in environmental carcinogenesis, warranting prioritized investigation into cytokine-pollutant crosstalk for cancer prevention strategies." (PMID 41226680, 2025). "In this model, when accounting for HA concentration at T0, the effect of the covariates: group, the administration of IV fluids before hospital admission, the presence of malignancy, IL-6 and ANP concentrations at T0 were not significant and they were removed from the model." (PMID 40512747, 2025). "Cytokines such as IL-15, IL-6, and EPI may directly inhibit cancer cell proliferation." (PMID 40699773, 2025). "CAF-derived cytokines, such as IL-6, IL-10, could activate the JAK/STAT pathways in cancer cells." (PMID 40517166, 2025). "In cytotoxic T cells/NK cells, we found that SUDV-induced IL-6 was predicted to induce SOCS3 expression and the downstream suppression of STAT5, granzyme B (GZMB) and PRF1 expression, leading to suppressed apoptosis of APCs and cancer cells, as well as pore formation." (PMID 41181097, 2025). "Because IL-6 is an upstream target of STAT3 and elevated IL-6 levels in cancer patients have prognostic significance regardless of the cancer type, several compounds targeting IL-6 or IL-6R have been developed and are used for both non-malignant and malignant diseases." (PMID 38339245, 2024). "The relationship between inflammation and muscle density has been reported in non-cancer populations, and attempts to define the mechanistic pathways suggest that cytokines such as TNF, IL-6, and IL-1β may stimulate proteolysis and inhibit anabolism, leading to muscle breakdown and wasting." (PMID 38512880, 2024). "A meta-analysis of the IL-6 serum concentration and prognosis in more than 11,000 patients with 23 different types of cancer in 100 studies concluded that the IL-6 serum concentration correlates with the prognosis in later stages, independent of cancer type." (PMID 39518029, 2024). "In cancer, the corresponding signal transduction after PRR stimulation amplifies the effect of the immunosuppressive response of MDSCs by producing a variety of proteins, including arginase-1, iNOS, IDO-1, prostaglandin E2, PD-L1, CD40, TNF-α, IL-1β, IL-6, cyclooxygenase-2, and others." (PMID 39035356, 2024). "Although therapies targeting the IL-6 axis have not met all expectations, combining them with other anticancer approaches or employing drugs with multiple targets in cancer ecosystems may prove beneficial in the hopefully near future." (PMID 39676864, 2024).